U6 (U6 spliceosomal RNA )
Synonyms: LOC124902567
Gene: Small nuclear RNA gene on chromosome 10 (102,868,421 to 102,868,519, forward strand). Ensembl gene ENSG00000283337.
Gene Ontology:
Molecular function: U4 snRNA binding
Biological process: formation of quadruple SL/U4/U5/U6 snRNP; spliceosomal tri-snRNP complex assembly
Cellular component: U4/U6 x U5 tri-snRNP complex; U6 snRNP
Homologues: Orthologues: chimpanzee U6 (96% identical), dog U6 (93% identical), macaque U6 (93% identical), rat LOC120095812 (89% identical). Paralogues in human: RNU6-11P (94% identical), RNU6-37P (94% identical), RNU6-25P (93% identical), RNU6-1 (92% identical), RNU6-140P (92% identical), RNU6-2 (92% identical), RNU6-35P (92% identical), RNU6-3P (92% identical), RNU6-43P (92% identical), RNU6-49P (92% identical), RNU6-4P (92% identical), RNU6-5P (92% identical), and 1289 more.